ARMH2 (armadillo like helical domain containing 2)
Synonyms: C6orf229
Tractability: No criterion of Open Targets' tractability assessment is met for any kind of drug.
Gene: Protein-coding gene on chromosome 6 (24,797,335 to 24,798,917, reverse strand). Ensembl gene ENSG00000260286.
Genetic constraint (gnomAD): Loss-of-function variants: 7 observed, 11.37 expected, observed/expected ratio (o/e) 0.62, 90% interval 0.35 to 1.16. The upper end of that interval is the gene's LOEUF score, 1.16, which puts it in group 5 of 6, group 1 being the genes least tolerant of losing a copy. Missense variants: 236 observed, 280.71 expected, observed/expected ratio (o/e) 0.84, 90% interval 0.75 to 0.94. Synonymous variants: 74 observed, 97.54 expected, observed/expected ratio (o/e) 0.76, 90% interval 0.63 to 0.92.
Homologues: Orthologues: chimpanzee ARMH2 (99% identical), pig ARMH2 (69% identical), dog ARMH2 (68% identical), rabbit ARMH2 (65% identical), rat Armh2 (56% identical), mouse Armh2 (53% identical).
Diseases named in the same sentence as ARMH2 in open-access papers:
ARMH2 is named in the same sentence as 1 disease in open-access papers, as found by Europe PMC text mining. Sharing a sentence is not in itself a finding about the gene and the disease. The quoted sentences say what the papers report.
asthenozoospermia (1 paper, 2025). "Loss of ARMH2 leads to compromised physiological activation of CatSper, thereby resulting in asthenozoospermia and severe subfertility." (PMID 41271765, 2025).